MYC (MYC proto-oncogene, bHLH transcription factor)
Diseases named in the same sentence as MYC in open-access papers (continued):
Sharing a sentence is not in itself a finding about the gene and the disease.
melanoma (continued). "Melanoma is a subtype of skin cancer, partly driven by the MAPK signaling pathway through RAS-RAF-MEK-ERK signaling, which concludes in the activation of ERK, and regulates p-STAT, MITF-M, c-MYC, and other transcription factors, resulting in alteration of cell proliferation and survival." (PMID 35756619, 2022). "Therefore, we speculated crosstalk between CDK1 and SOX2/MYC in melanoma, and silenced SOX2 in human melanoma cells." (PMID 31080551, 2019). "However, the strong expression levels of c-MYC (1564 bp), Sestrin-1 (1253 bp), and SRPX2 (1274 bp) irregular transcripts indicate their ability to escape the NMD quality control system operating in melanoma cells." (PMID 30795533, 2019). "Interestingly, MYC has been shown to override activated BRAF-induced senescence and partially inhibit NRAS-induced senescence in human normal melanocytes, and depletion of MYC induced senescence in melanomas with activated BRAF/NRAS." (PMID 30526305, 2018). "E2F1 levels were not altered by MYC-depletion in melanoma cells indicating that under-expression of TS and RR and depletion of dNTP pools in senescent melanoma cells is likely to be a direct consequence of C-MYC suppression." (PMID 23249808, 2012). "However, we could not demonstrate co-immunoprecipitation of endogenous BRAF with RAF1, or transiently transfected MYC and FLAG tagged RAF1 in PLX4032-treated melanoma cells under conditions in which RAF1 was activated by the drug." (PMID 20149136, 2010). "A potential explanation for this mild effect may be c-MYC expression that we find in BXB11 tumor cells and that has been recently described to revert a sensescence phenotype in B-RAF transformed melanomas." (PMID 19156217, 2009). "Therefore, the absence of c-MYC regular transcriptional activity in melanoma, but not in BCC and SCC biopsies, may render cells vulnerable to an intron retention process." (PMID 30795533, 2019). "In melanoma, a previous study failed to rescue the growth-inhibitory phenotype of BRD4 deletion with MYC overexpression 33, suggesting that MYC is not the main target of BRD4 in melanoma." (PMID 38169595, 2024). "The collection of c-MYC, Sestrin-1, and SRPX2 nonspliced transcripts clearly typify human melanoma and molecularly differentiate it from BCC and SCC skin cancers." (PMID 30795533, 2019). "DANCR may play an essential role in melanoma downstream of MITF and c-MYC irrespective of tumour genomic status." (PMID 41336739, 2025). "Therefore, in our study, we chose c‐MYC as a loading control for nuclear fraction of proteins, since it shows nuclear distribution and is not affected by MX2 downregulation in melanoma cells." (PMID 33734579, 2021).
ovarian carcinoma (322 papers, 2001 to 2026). A malignant neoplasm originating from the surface ovarian epithelium. "In our study, we analyzed the polymorphisms and expressions of the BCL2, BAX and c-MYC genes in patients with ovarian cancer." (PMID 38003498, 2023). "In a recent study conducted using 64 early staged epithelial ovarian cancer tissues and 20 normal ovarian tissues, the expression of two genes—c-MYC and Plasmacytoma Variant Translocation 1 (PVT1)—was studied." (PMID 37110218, 2023). "The aim of this study is to analyze the polymorphisms and expressions of the BCL2, BAX and c-MYC genes in patients with ovarian cancer." (PMID 38003498, 2023). "The Indian Cohort showed MUC16, MUC4, and CIITA to be most mutated and carry CNV in the same genes apart from MYC, which is known to be amplified in most cancers, including ovarian cancer." (PMID 37091785, 2023). "The tumor-promoting polyamine pathway is tightly linked to c-MYC signaling and intertwines with the malignancy of ovarian cancer." (PMID 36765581, 2023). "In vitro and in vivo ovarian cancer models combining PARPi with CDK 4/6 showed synergistic effects with palbociclib by inducing HRR deficiency through downregulation of MYC-regulated HR pathway genes, leading to synthetic lethality with olaparib." (PMID 36401316, 2022). "MiR-145 overexpression reduces proliferation, migration, and invasion of epithelial ovarian cancer cells that was associated with a decrease in the levels of c-MYC and VEGF proteins." (PMID 35330327, 2022). "Our findings reveal a MYC-driven plasma polyamine signature associated with OvCa that complemented CA125 in detecting early-stage ovarian cancer." (PMID 33671595, 2021). "In human ovarian tumors, amplification of MYC is common, and high expression of MYC is associated with platinum resistance in ovarian cancer." (PMID 34645978, 2021). "Dual inhibition of PARP (Olaparib) and CDK4/6 (Palbociclib) inhibits the growth of ovarian cancer cells in vitro and slows down tumor growth in vivo in part by inducing homologous recombination (HR) deficiency in a MYC-dependent manner." (PMID 33718147, 2021). "To explore the underlying mechanism of calcitriol regulation of MYC in ovarian cancer cells, we studied the interaction of CCAT2 and TCF4 at the MYC promoter." (PMID 32230936, 2020). "Both disease-free and overall survival of ovarian cancer patients as negatively associated with high MYC expression and high MYC levels are associated with platinum resistance." (PMID 30626133, 2019). "Another report found an association between c-MYC amplification (> 4 copies/cell in a minimum of 10% of tumor cells) and the advanced stages of ovarian cancer." (PMID 26426996, 2015). "Genes rearranged in ovarian cancer are highly linked to vital genes like MYC, BRCA1, and PAX6 that were also altered in ovarian cancer." (PMID 22811706, 2012). "Surprisingly, on 8q24 both the GISTIC and frequency peaks were located ∼500 kb distally to the two previously implicated oncogenes in ovarian cancer within this locus, MYC and PVT1." (PMID 20844748, 2010). "A detailed mapping of SNPs at a locus on chromosome 8q, near MYC, has recently provided substantial evidence that this locus is associated with susceptibility to breast, prostate and ovarian cancer." (PMID 19240718, 2009). "Moreover, a previous study revealed that the MYC target v1, which is associated with cell proliferation, was positively correlated with ovarian cancer." (PMID 39135097, 2024).
ovarian carcinoma (continued). "Nowadays, only mutations in ARID1A have been more comprehensively studied in ovarian cancer, explaining not only that their mutations cause an increase in MYC expression and affect tumour progression, but also that therapies targeting ARID1A mutations have emerged in the clinic." (PMID 36883311, 2023). "Also, resistance to TGFβ – an antiproliferative growth factor – coincides with the loss of c-MYC repression in ovarian carcinoma cells." (PMID 33718147, 2021). "Indeed, high levels of oncogenic c-MYC are found in 65% of human ovarian cancers and are associated with the activation of stem cell-like potential, faster recurrence, platinum resistance, and the poor overall survival of ovarian cancer patients." (PMID 35736348, 2022). "However, despite the fact that MYC mRNA expression was associated with survival in The Cancer Genome Atlas dataset, the correlation of MYC amplification to ovarian cancer prognosis remains unclear." (PMID 35965534, 2022). "The current study is the first to show genome binding patterns for both HSF1 and MYC in co-amplified ovarian cancer cells." (PMID 39831777, 2025). "In ovarian cancer, MYC plays a critical role in tumor progression by promoting metabolic reprogramming, chemoresistance, and invasion, making it a key factor in disease recurrence and poor survival rates." (PMID 40365020, 2025). "For example, BMAL1 overexpression in ovarian cancer cell lines reduced tumor growth and restored c-MYC rhythmicity." (PMID 41142939, 2025). "c-MYC is significantly upregulated in ovarian cancer and inhibits ferroptosis and ROS in ovarian cancer cells." (PMID 39039611, 2024). "A combination of a CDK4/6 inhibitor palbociclib with olaparib in ovarian cancer cell models demonstrated a synergistic effect in MYC-overexpressing cells, presumably via palbociclib-induced HRD." (PMID 39594684, 2024). "Elevated tumor c-MYC mRNA levels were prognostic for poor disease-free survival and worse overall survival in The Cancer Genome Atlas (TCGA) ovarian cancer dataset." (PMID 36765581, 2023). "It has been demonstrated that ovarian cancer cells highly rely on MYC for maintaining their oncogenic growth, and MYC is a therapeutic target for ovarian cancer." (PMID 37221474, 2023). "Analysis of the same cohort of patients form the PanCancer project showed that CDK12 and CDK13 deep deletions are mutually exclusive with MYC amplification in ovarian cancer." (PMID 37202753, 2023). "In one of the first studies conducted to determine the role of c-MYC in ovarian cancer, this gene was amplified in ovarian cancer cell lines." (PMID 37110218, 2023). "In ovarian cancer, proto-oncogene serine/threonine-protein kinase Pim-1 interacts with c-MYC and mediates its Ser62 phosphorylation, promoting cancer cell proliferation." (PMID 36765581, 2023). "A small molecule 10058-F4 blocks c-MYC/MAX heterodimerization in ovarian cancer cells and thus induces cell cycle arrest and apoptosis and attenuates glutamine uptake, an essential nutrient for cancer cells." (PMID 36765581, 2023). "Herein, we discuss the involvement of c-MYC signaling and that of its paralogues in promoting ovarian cancer tumorigenesis." (PMID 36765581, 2023). "Deregulation of c-MYC was a triggering factor for oncogenesis in cancers, especially in ovarian cancers." (PMID 37110218, 2023). "We found that the effect of IACS-010759 treatment on MYC levels is conserved across cells from different tumor types including, colorectal, breast, and ovarian carcinoma." (PMID 37130865, 2023). "Recent evidence indicated that ovarian cancer cells depend on the oncogenic transcription factor MYC for their growth and survival." (PMID 37202753, 2023). "This is the first study in the Polish population to take into account the analysis of the c-MYC gene expression level and protein level in ovarian cancer." (PMID 38003498, 2023).
ovarian carcinoma (continued). "Several studies have assessed the prognostic value of c-MYC copy-number amplification as well as mRNA expression and protein levels in ovarian cancer." (PMID 36765581, 2023). "This review informs on how the MYC signaling is dysregulated and participates in ovarian cancer progression, and the unmet challenge to directly target MYC for ovarian cancer treatment." (PMID 36765581, 2023). "Dual inhibition of PARP and CDK4/6 suppressed ovarian cancer cell growth in vitro and tumor growth in vivo in a c-MYC-dependent manner." (PMID 36765581, 2023). "The MYC gene was amplified in 9% of total tumors and most amplified (32%) in ovarian cancer (serous)." (PMID 37298484, 2023). "In the ovarian cancer dataset, MYC Targets V2 was in fact the only significantly upregulated gene set." (PMID 36692000, 2023). "Amplification of genes between 18 Mb up- and downstream of the MYC gene (Ch 8q24.21) in ovarian cancer was examined (left)." (PMID 37298484, 2023). "The insulin-like growth factor II mRNA-binding protein 1 (IGF2BP1/IMP1) inhibitor BTYNB destabilizes c-MYC mRNA via disrupting IMP1 binding to c-MYC mRNA, thereby repressing ovarian cancer cell proliferation." (PMID 36765581, 2023). "Signaling pathways upstream of the module ribosome biogenesis, including the PI3K/AKT/mTORC1 and RAS/MAPK signaling pathways and the c-MYC proto-oncogene “super” growth regulatory network, are aberrantly regulated and activated in ovarian cancer." (PMID 37684587, 2023). "Early investigations demonstrated anti-ovarian cancer efficacy by targeting c-MYC using triplex-forming and liposomal phosphorothioate oligonucleotides in vitro." (PMID 36765581, 2023). "A 38.5% increase in the copy number of the c-MYC was discovered to play a role in development of ovarian cancer." (PMID 37110218, 2023). "c-MYC is another oncogene that is significantly amplified and has high copy number variations in ovarian cancer and plays an important role in deregulating glycolysis." (PMID 37110218, 2023). "We additionally highlight opportunities for exploiting c-MYC-driven polyamine metabolism for early detection and therapeutic applications in ovarian cancer." (PMID 36765581, 2023). "We highlight the potential of targeting c-MYC-driven polyamine metabolism for the treatment of ovarian cancers and the utility of polyamine signatures in biofluids for early detection applications." (PMID 36765581, 2023). "c-MYC copy-number amplifications have been reported in up to 50% of ovarian carcinomas, whereas MYCL copy-number amplifications and gene overexpression have been reported in upwards of 21% of ovarian carcinomas." (PMID 36765581, 2023). "Wang found that ovarian cancer patients with c-MYC copy-number amplifications had poorer overall survival compared to those with wild-type c-MYC." (PMID 36765581, 2023). "The oncogene c-MYC, which is aberrantly expressed in ovarian cancer, was observed to regulate TCA either directly or indirectly." (PMID 37110218, 2023). "In line with a dual role for BDP1 dependent on the mutational profile of the cancer, we recognize that ovarian cancer cells depend on MYC for maintaining their oncogenic growth and is amplified in 30–60% of all ovarian cancers." (PMID 36305848, 2023). "c-MYC and its paralogues are among the most frequently amplified and/or overexpressed oncoproteins in ovarian cancer." (PMID 36765581, 2023). "Our study found that ME treatment effectively reversed HSP90AB1 overexpression, downregulated the expression of cancer-related factors IGF1R and MYC, and exerted anti-tumorigenic effects in ovarian cancer." (PMID 36362498, 2022).
ovarian carcinoma (continued). "Celastrol directly interacted with MYC to regulate cell proliferation, DNA repair and replication, and apoptosis in ovarian cancer cells." (PMID 35370699, 2022). "NGF (nerve growth factor) increases its expression during the progression of epithelial ovarian cancer, promoting cell proliferation and increasing vascularization through several oncogenic proteins such as c-MYC and VEGF." (PMID 35330327, 2022). "Here we demonstrate that PVT1 is a contextual oncogenic lncRNA, amplified along with MYC, and a prognostic indicator in ovarian cancers that is dynamically altered in expression primarily in response to cellular stressors." (PMID 35820706, 2022). "For example, THZ1 also inhibits the transcriptional regulators CDK12 and CDK13, and combined inhibition of CDK7/12/13 was required to suppress MYC expression in ovarian cancers harboring MYC amplification." (PMID 36214609, 2022). "Surprisingly, we discovered that induced persistent upregulation of MYC in TNBC and ovarian cancer cells is associated with sensitivity to TOP1 inhibitors but not TOP2 inhibitors." (PMID 35844787, 2022). "Recently, therapeutic synergy for combination of PARPi and CDK4/6i has been demonstrated in MYC highly expressed breast and ovarian cancers with HR proficiency, which provides a new synthetic lethal strategy for treatment of these cancers regardless HR status." (PMID 35270034, 2022). "In a cohort-wide analysis, multiple genomic regions containing recurring amplifications and deletions were identified, encompassing copy number gains in genes marked as drivers in ovarian cancer such as MYC and CCNE1." (PMID 35326660, 2022). "A close correlation of MYC with chemoresistance can be found in colorectal, gastric, and ovarian cancers." (PMID 35739532, 2022). "SALL2 binds target genes, BAX, p16, and c-MYC in ovarian cancer through the canonical GC-rich motif." (PMID 36438565, 2022). "Lately, it has been shown that miR-145 inhibits glutaminolysis in ovarian cancer cells by decreasing the expression of c-MYC, which lowers GLS transcription." (PMID 36483029, 2022). "We find a strong correlation between PVT1 and MYC in ovarian cancer, as has been previously documented." (PMID 35820706, 2022). "SiRNA-mediated c-MYC knockdown in MYC-amplified ovarian cancer cells inhibits proliferation and induces replicative senescence by increasing the Cdk inhibitor p27 and decreasing CDK2 activity." (PMID 33718147, 2021). "In fact, evidence indicates that PTOs against c-MYC inhibit the proliferative effect of TGFα in ovarian cancer cells." (PMID 33718147, 2021). "Increasing miR-145 levels negatively regulates PD-L1 by repressing c-MYC expression in cisplatin-resistant ovarian cancer cells." (PMID 33718147, 2021). "Inhibition of GLS—a downstream target of c-MYC—by CB-839 sensitizes ovarian cancer cells to PARP inhibition and prolong survival in tumor-bearing mice." (PMID 33718147, 2021). "Active c-MYC-miR-137-EZH2 was also confirmed in tumor samples from recurrent patients with ovarian cancer." (PMID 33718147, 2021). "Blocking c-MYC/MAX heterodimerization with the small-molecule inhibitor 10058-F4 significantly inhibits ovarian cancer cell proliferation in part by inducing apoptosis and cell cycle arrest." (PMID 33718147, 2021). "In fact, integrated genomic analyses of ovarian carcinoma revealed that one of the most common focal amplifications resides within the region containing c-MYC." (PMID 33718147, 2021). "Chromatin immunoprecipitation experiments showed that BRD4 binds directly to MYC transcription start site, as well as enhancer regions in ovarian cancer cells." (PMID 34758842, 2021). "Concomitant upregulation of glutaminase (GLS) and c-MYC has been observed in platinum-resistant ovarian cancer cells." (PMID 33718147, 2021). "Given the pivotal role of c-MYC deregulation in most tumor types, including ovarian cancer, assessment of c-MYC biological and clinical relevance is essential." (PMID 33718147, 2021).